TNF (tumor necrosis factor)
Diseases named in the same sentence as TNF in open-access papers (continued):
Sharing a sentence is not in itself a finding about the gene and the disease.
Cirrhosis (continued). "The level of TNF-α was found to be elevated in patients with cirrhosis or acute/chronic hepatitis when compared with healthy patients in different studies." (PMID 35594248, 2022). "The HCC timepoint was characterized by a significant increase in interferon-gamma (IFN-γ), tumour necrosis factor alpha (TNF-α), IL-6 and IL-17 compared to inflammation and cirrhosis timepoints (all P < 0.05)." (PMID 33858327, 2021). "Activation of systemic, renal tissue and renal vessel levels of PPARγ by chronic pioglitazone treatment has beneficial effects on the endotoxemia-related TNFα/NFκB-mediated acute on chronic renal inflammation in cirrhosis." (PMID 34831270, 2021). "Reductions in HLA-DR expression and in vivo production of TNF-α have been described in patients with advanced cirrhosis." (PMID 33389680, 2021). "In advanced cirrhosis, persistent increased circulating tumor necrosis factor-α (TNFα)-related bacterial translocation and systemic (hepatic, intestinal, renal) inflammation are involved in the development of intestinal/renal dysfunction and HRS." (PMID 33513830, 2021). "In advanced cirrhosis, the TNFα-mediated intestinal inflammation and bacteria dysbiosis are involved in the development of inflammation and vasoconstriction-related renal dysfunction." (PMID 33513830, 2021). "The serum levels of NF-ĸB, TNF-α and IL-6 are indicators of inflammation in the cirrhosis and they were increased significantly in the BDL group compared to the control group (p < 0.01)." (PMID 34567144, 2021). "Renal expression of lipocalin-2 is significantly increased in decompensated cirrhosis with increased circulating TNFα and acute renal injury." (PMID 33513830, 2021). "Activation of systemic, renal vessel and renal tissue levels of PPARγ by chronic pioglitazone treatment has beneficial effects on the endotoxemia-related TNFα/NFκB-mediated acute and chronic renal inflammation in cirrhosis." (PMID 34831270, 2021). "The serum NF-κB, TNF-α and IL-6 levels of all groups in the cirrhosis model formed by bile duct ligation (BDL) in rats (n = 6; mean ± SD)." (PMID 34567144, 2021). "Agents that can restore intestinal SIRT1 have the potential to improve the inflammation-derived TNFα-mediated renal dysfunction in advanced cirrhosis." (PMID 33513830, 2021). "TNF-α and IL-6 production was reduced in cirrhosis compared with HC and incrementally decreased from Child A to C, and AD but remained preserved in patients with CLD without cirrhosis." (PMID 31822557, 2020). "Both, BGB324 (1 μM) and metformin (10 mM) treatment restored LPS-induced TNF-α production of monocytes from patients with cirrhosis ex vivo." (PMID 31822557, 2020). "Circulating monocytes from patients with AD and ACLF compared with stable cirrhosis demonstrated reduced expression of HLA-DR and attenuated production of TNF-α/IL-6 in response to lipopolysaccharide (LPS), which has previously been linked to adverse outcome." (PMID 31822557, 2020). "TNF-α/IL-6 responses to lipopolysaccharide were attenuated in monocytes from patients with cirrhosis (n = 96) compared with controls (n = 27) and decreased in parallel with disease severity." (PMID 31822557, 2020). "SBP is common in patients with cirrhosis and ascites, and cirrhotic patients are likely to have an infection that activates cytokines like tumor necrosis factor (TNF)-α, interleukin (IL)-6, and IL-1 affecting circulation and coagulation pathway." (PMID 32566430, 2020). "The NLR has been described widely as a predictor of HA bacterial infections in decompensated cirrhosis, and it correlates with tumor necrosis factor alpha (TNF-α) and interleukin 6 (IL-6) concentrations." (PMID 32155772, 2020). "Ex vivo: Plasma from DC and ACLF led to decreased LPS-stimulated TNFα release and bacterial killing when incubated with healthy monocyte-macrophages, compared to plasma from stable cirrhosis." (PMID 30804947, 2019).
Cirrhosis (continued). "Although the interplay between CD8+T cells and neutrophils have been previously demonstrated, our study is the first to report an immunomodulatory role of dysfunctional CD8+T cells on PMNs in cirrhosis, particularly in regards to TNF-α secretion." (PMID 31678004, 2019). "TNF‐α levels in the liver, as a marker for inflammation, were significantly higher in mice with cirrhosis compared to mice with fibrosis or a healthy liver." (PMID 31245923, 2019). "In early chronic liver disease as well as compensated and decompensated cirrhosis, elevated spontaneous and/or LPS-induced monocyte TNF production have been identified." (PMID 30873165, 2019). "Bowel decontamination was also able to normalize dendritic cell dysfunction and increase TNF-α production in experimental cirrhosis." (PMID 31118937, 2019). "Ex vivo: Increased activation markers (HLA-DR and CD80) and intracytoplasmic TNFα expression in monocytes from cirrhosis (DC) compared to HC." (PMID 30804947, 2019). "In cirrhosis, higher levels of systemic inflammatory cytokines including TNF-α, IL-1, and IL-6 have been reported." (PMID 31392488, 2019). "In our study, Th1 cells and Th2 cells showed a significant increase after PSE in patients with cirrhosis, with serum levels of TNF-alpha, sTNFr-I, and sFas also increasing significantly." (PMID 30116748, 2018). "The pro-inflammatory cytokines, TNF and IL-6, are elevated in cirrhosis patients and increase further in the context of infection." (PMID 29263339, 2017). "Proinflammatory cytokines, such as interleukin-1 and -6 or tumor necrosis factor α (TNF-α), are involved in the pathogenesis of hepatic cirrhosis." (PMID 28430124, 2017). "During cirrhosis, persistent intestinal mucosal inflammatory injury results in a stimulation of TNFα production by gut-derived endotoxin activated inflammatory cells." (PMID 26820153, 2016). "Our study explored the roles of intestinal and mesenteric TNFα along with inflammasome-related pathway in relation to cirrhosis and the splanchnic/collateral microcirculation." (PMID 26820153, 2016). "When there is a chronic inflammatory disease like cirrhosis present, TNFα brings about the stimulation of VEGF and NO-derived angiogenesis in order to supply nutrients and oxygen to the affected tissue." (PMID 26820153, 2016). "The other study assessing the role of NF-κB in mediating systolic dysfunction in cirrhosis showed an improvement of diastolic relaxation in cardiomyocytes when its inhibitors blocked NF-κB activity, with reduction in TNF-α expression." (PMID 26665009, 2015). "TNFα plays a critical role in the inflammatory environment and it is considered to be one of the main factors leading to cirrhosis." (PMID 26121590, 2015). "Serum TNF-α levels were higher in the Child-Pugh class C cirrhosis than in the Child-Pugh class A cirrhosis (P < 0.05)." (PMID 26665009, 2015). "The changes in cardiac function during cirrhotic cardiomyopathy are more evident in decompensated cirrhosis, and TNF-α is key factor in the signaling pathways regulating myocardial dysfunction." (PMID 26665009, 2015). "In experimental cirrhosis of rats, albumin exerted a positive cardiac inotropic effect counteracting oxidative stress- and TNF-a-induced impairment of cardiac contractility." (PMID 26606982, 2015). "Independent variables were age, sex, IL28B, −238 TNF-α and −592 IL-10 polymorphisms, HCV genotype, HCV-RNA levels, significant fibrosis or cirrhosis and CD4+ T cell count." (PMID 25013899, 2014). "Elevated bile acid and TNF-α levels in plasma are found in human cirrhosis and in animal models including CBDL and are recognized to induce cell apoptosis through the activation of extrinsic or intrinsic pathways in a number of cell types." (PMID 25419825, 2014). "TGF-β1 and TNF-α levels were significantly elevated (P<0.001) in serum samples from the cirrhosis Group 2 (100.11 ± 10.67 and 343.41 ± 4.66 pg/mL, respectively) compared with all other groups." (PMID 23496995, 2013).
Cirrhosis (continued). "With this objective, we have assessed the influence of TNF-α and IL-10 single nucleotide polymorphisms on the progression of HCV-induced chronic hepatitis to cirrhosis in HIV-coinfected patients." (PMID 23840511, 2013). "It is well known that the levels of many proinflammatory cytokines (TNF-alpha, IL-6, IL-1β, etc.)are higher in the plasma of patients with cirrhosis than in that of healthy subjects." (PMID 23326675, 2012). "On the other hand, we revealed that the free amino acid concentration L-Cystine (L-Cys) correlated inversely with the glomerulus filtration rate (eGFR) in patients with cirrhosis, and high levels of L-Cys increase the production of TNF-alpha from monocytes." (PMID 23326675, 2012). "A plasma L-Cys/L-Glu imbalance, which appears in patients with advanced cirrhosis, increased the TNF-alpha from circulating monocytes via increasing the intracellular oxidative stress." (PMID 21858100, 2011). "In patients with advanced cirrhosis (n = 19), the TNF-alpha and xCT mRNA of monocytes were increased according to the Child-Pugh grade." (PMID 21858100, 2011). "Circulating levels of proinflammatory cytokines such as TNF-alpha, IL-1 beta and IL-6 are increased in patients with cirrhosis." (PMID 21858100, 2011). "IL-6 is a multifunctional cytokine along with TNF-α activates hepatic stellate cells and increases the production of extracellular matrix proteins that finally leads to cirrhosis." (PMID 22013498, 2011). "Therapies targeting Trm cells or the TNF-α signaling pathway could be explored to delay progression to cirrhosis in BA." (PMID 40607400, 2025). "Consistent with previous findings, we observed that the FSTL1 levels were elevated in the serum of cirrhosis patients and in carbon tetrachloride (CCl4)-induced model mice and were positively correlated with the serum TGF-β1, TNF-α and IL-6 levels in cirrhosis patients." (PMID 40050288, 2025). "Low-grade cirrhosis-associated immune dysfunction is present in cirrhotic patients without ACLF and is characterized by the production of pro-inflammatory cytokines such as Il-1β, IL-6, TNF-α and INF-γ." (PMID 39861356, 2025). "Also, in patients with decompensated cirrhosis, there is a marked increase in proinflammatory cytokines such TNFα and IL-6." (PMID 38551716, 2024). "The blood levels of DAO were significantly inversely correlated with blood levels of claudin 3 (r = −0.373; p = 0.002), LPS (r = −0.275; p = 0.027), presepsin (r = −0.310; p = 0.012), TNF-α (r = −0.310; p = 0.012), and the severity of cirrhosis according to Child–Pugh scores (r = −0.249; p = 0.045)." (PMID 38543514, 2024). "SB reduced the serum concentrations of TNF-α, IL-1β, IL-6, and IL-4 in animals with metabolic dysfunction-associated steatotic liver disease (MASLD); lowered the serum TNF-α and IL-6 levels in experimental cirrhosis in rats; and reduced the CRP levels in decompensated cirrhosis." (PMID 39203520, 2024). "In a rat model of cirrhosis due to bile duct ligation, N-Lac treatment could decrease the galectin-3 and TNF-α contents in the heart." (PMID 38275628, 2023). "Nonetheless, the exact role of TNF-α in HCC and, more specifically, in NAFLD-associated HCC, remains largely understudied, which is consistent with our knowledge gaps pertaining to the mechanisms of progression from NASH or liver fibrosis/cirrhosis to HCC." (PMID 37958479, 2023). "Furthermore, the administration of rifaximin for 4–12 weeks has been shown to decrease the blood levels of IL-6, IL-10, and TNF-α in patients with nonalcoholic fatty liver disease and cirrhosis with HE." (PMID 36983211, 2023). "Cytokine levels of IFN-α2, IFN-γ, TNF-α, IL-6, IL-8, IL-10, IL-17A, IL-18, IL-23, and IL-33 were significantly elevated in patients with decompensated cirrhosis compared to patients with compensated cirrhosis." (PMID 38077228, 2023). "Stratified analyses of TNF-α and IFN-γ genes’ common polymorphisms on cirrhosis of liver risk." (PMID 37122734, 2023).
Cirrhosis (continued). "Interrupting interactions between CEACAM1 and TNFα might prove effective in preventing cirrhosis-related hyperpermeability." (PMID 36741860, 2023). "For example, activated hepatic macrophages produce cytokines, such as IL-6, IL-1β, TNF-α and macrophage colony-stimulating factor (M-CSF), which sustain their pro-cirrhosis and pro-inflammatory activities while also stimulating HSCs to form an inflammatory cascade." (PMID 38275754, 2023). "Patients with alcoholic hepatitis and/or cirrhosis show elevated serum concentration levels of TNF-alpha and TNF-alpha-inducible cytokines/chemokines, such as IL-6, -8, and -18, and levels correlated with markers of the acute phase response, liver function, and clinical outcome." (PMID 35269779, 2022). "Increased levels of the proinflammatory cytokines tumor necrosis factor-alpha (TNFa), interleukin-1, and interleukin-6 might influence the hemodynamic alterations of patients with cirrhosis." (PMID 35269779, 2022). "Functionally these activated macrophages were responsive to microbial challenges, which resulted in the production of pro-inflammatory cytokines (IL-23, IL-6, and TNF-α) and contribute to mucosal, epithelial, vascular and immunological barrier dysfunction in cirrhosis." (PMID 36926073, 2022). "This indicates that the feedback loop between PIM2 and TNFα maybe a driven force between chronic liver inflammation and cirrhosis." (PMID 32641749, 2020). "Rifaximin could reduce the concentrations of TNF-α, IL-6, and endotoxin in patients with decompensated cirrhosis." (PMID 32759852, 2020). "Furthermore, TNF-α plays a pivotal role in increasing NO in cirrhosis and also in NO overproduction." (PMID 32128089, 2019). "In fact, cirrhotic livers are abnormally sensitive to in vivo LPS-induced TNFα-mediated apoptosis, due to an altered unfolded protein response, which might contribute to liver damage under bacterial challenge in cirrhosis." (PMID 31118937, 2019). "Ex vivo: Microarray gene expression profiling of PBMCs from ARLD cirrhosis (DC) compared to HC, showed increased induction of pro-inflammatory cytokine genes (IL-6, IL-8, TNFα), but decreased induction of type-1 and type-2 IFN-stimulated genes, compared to HC (see right column)." (PMID 30804947, 2019). "Development of cirrhosis in some patients could be related to inflammation mediated by TNFα and IL-1β." (PMID 31118107, 2019). "Baseline serum TNFα concentrations were significantly increased in both cirrhosis models (OO 20.5 ± 0.5 pg/ml versus 16-wk CCl4 1,102 ± 270 pg/ml, d = 1,081, 95% CI 470, 1,693, p < 0.001; sham 727 ± 219 pg/ml versus BDL 4,006 ± 247 pg/ml, d = 3,279, 95% CI 1,417, 5,141, p < 0.001)." (PMID 28245243, 2017). "Cortex phellodendri is anti-inflammatory in nature, which helps to eliminate invading pathogens, ameliorates acetaldehyde-induced hepatic NF-κB activation during cirrhosis, and inhibits glial proinflammatory iNOS (nitric oxide synthase) and TNF (tumor necrosis factor)-α activity." (PMID 26999089, 2016). "We hypothesize that patients with schistosomiasis have less marked vasodilatation than observed in cirrhosis from differences in the concentrations of vasoactive mediators, such as endothelin and tumor necrosis factor." (PMID 27119143, 2016). "This suggests that an inflammatory milieu, with increased TNF-α levels, may also be partly responsible for the diastolic dysfunction in cirrhosis, but the exact mechanism with which TNF-α affects diastolic dysfunction has not been elucidated." (PMID 26665009, 2015). "TNF-α and IL-6 levels could be used to differentiate between patients with compensated cirrhosis and patients with de-compensated alcoholic cirrhosis." (PMID 26343741, 2015). "And previous report has shown that serum TNF-α levels correlate with the severity of cirrhosis." (PMID 26039496, 2015).
Cirrhosis (continued). "Systemic inflammation is a major characteristic of cirrhosis and other chronic liver diseases with increased levels of pro-inflammatory cytokines and chemokines such as TNF-α and IL-6, which in turn can disrupt the integrity and function of the intestinal epithelial barrier." (PMID 25171482, 2014). "Furthermore, alveolar macrophage NOS is upregulated by increased levels of tumor necrosis factor-alpha (TNF-α) in cirrhosis and HPS." (PMID 24102057, 2013). "In addition, the pro-inflammatory cytokine TNF-α was elevated in the cirrhosis rats indicating a high inflammatory state in the cirrhotic liver." (PMID 23496995, 2013). "Furthermore, we reported that the mRNA expression of TNF-alpha and xCT were significantly higher in monocytes of patients with decompensated cirrhosis than in those of healthy volunteer." (PMID 23326675, 2012). "Finally, we actually measured the levels of TNF-alpha of patients with advanced cirrhosis in monocytes and plasma." (PMID 21858100, 2011). "TNF-alpha is known to be involved in bacterial translocation in rats with cirrhosis." (PMID 20653983, 2010). "TNF-α is involved in the occurrence of bacterial translocation in rats with cirrhosis." (PMID 18782455, 2008). "Patients with cirrhosis are highly susceptible to Gram-negative bacterial infections, which cause excessive release of the pro-inflammatory cytokine tumor necrosis factor-alpha (TNF-alpha), exacerbating liver damage." (PMID 40563298, 2025). "Therefore, we explored the effect of the pro‐inflammatory properties of IL‐2‐330 (rs2069762), IL‐8 (rs2227306), TNF‐α−857 (rs1799724), and TNF‐α−1031 (rs1799964) versus the anti‐inflammatory properties of IL‐10‐1082 (rs1800896), IL‐10‐592 (rs1800872) on the risk of cirrhosis." (PMID 39315805, 2024). "While cirrhosis evolves into an ascitic stage, the intestinal immune system in cirrhotic rats undergoes a shift toward a Th1 regulatory pattern, marked by the expansion of TNF-α- and IFN-γ-expressing lymphocytes, and the concomitant depletion of Th17 cells in the lamina propria." (PMID 38613058, 2024). "Patients with cirrhosis due to viral hepatitis showed increased numbers of hepatic macrophages associated with the infiltration of other pro-inflammatory CD14+HLA-DRhiCD206+ myeloid cells, which in turn produced pro-inflammatory cytokines such as IL-1β, IL-18, and TNF-α." (PMID 36926073, 2022). "In mice with advanced cirrhosis, the expression of intestinal SIRT1 is involved in the linkage between intestinal dysbiosis and vasoconstriction/hypoperfusion-related renal dysfunction through the crosstalk between intestinal/renal TNFα-related pathogenic inflammatory signals." (PMID 33513830, 2021). "Additionally, we found a feedback loop between TSG-6, MMP12 and pro-inflammatory cytokines (TNF-α, IL-6, and IL-1β), which may improve our understanding of the aggravating process of cirrhosis and antifibrotic mechanisms of TSG-6 and MSCs." (PMID 31903104, 2020). "Therefore, low TNF-alpha levels in patients with compensated cirrhosis may reflect an insufficient TNF-alpha production in the liver, playing a role in subclinical liver failure in these patients." (PMID 30941129, 2019). "TGF-β is anti-inflammatory and involved in inhibiting apoptosis, while TNF-α, IL-8, FGF2, and VEGFA are involved in hepatic injury or cirrhosis through cell proliferative and angiogenic activities." (PMID 41219858, 2025). "Other studies have reported that tumor necrosis factor-alpha (TNF-α), a key marker of cirrhosis and HCC development, is correlated with the secretion of IL-6." (PMID 41219858, 2025). "In cirrhosis, CD14+CD16+ monocytes increase, expressing more TNF, determining a pro-inflammatory and profibrogenic phenotype." (PMID 38473721, 2024). "In hepatic cirrhosis, TLR4-LPS interaction determines TNF, IL-1, IL-6 pro-inflammatory cytokines, and chemokines production." (PMID 38473721, 2024).